REST (RE1 silencing transcription factor)
Diseases named in the same sentence as REST in open-access papers (continued):
Sharing a sentence is not in itself a finding about the gene and the disease.
neuroblastoma (35 papers, 2012 to 2025). Neuroblastoma (NB) is the most common solid, extracranial childhood tumor. "It was found that the loss of lncRNA neuroblastoma-associated transcript-1 (NBAT-1) contributed to aggressive neuroblastoma by activating REST." (PMID 37892159, 2023). "REST has also been implicated as a tumor suppressor in breast cancer, colorectal cancer and small cell lung cancer, and as an oncogene in neuroblastomas, medulloblastomas and pheochromocytomas, which are associated with von Hippel-Lindau syndrome." (PMID 24922058, 2014). "The SK-N-SH cell line is particularly interesting as it allows us to perform a comparison between normal neurons and tumorgenetic neuroblastoma cells, which have been reported to be associated with increased REST expression." (PMID 24922058, 2014). "The enhanced REST activity in neuroblastoma is found to be associated with higher clinical stages and the loss of heterozygosity on chromosome 11q23, a feature of high-risk neuroblastomas." (PMID 40006989, 2025). "We explored the exon array’s ability to detect known truncated splice variants associated with reduced REST activity, given that probe-set 2728423 targeted the 50-62bp cryptic exon found in neuroblastoma (hREST-N62), small cell lung cancer (sREST), and presumably NEPC." (PMID 29132337, 2017). "It has been reported that elevated expression of REST is associated with neuroblastomas." (PMID 24922058, 2014). "In human medulloblastomas and neuroblastomas, the RE1-silencing transcription factor (REST) plays the role of an oncogene and evades β-TrCP1-mediated degradation by C-terminal truncations." (PMID 37686524, 2023). "In neuroblastoma, REST protein levels are aberrantly elevated, at least in part due to loss or decline in expression of the ubiquitin E3-ligase, SCF-β-TRCP and a failure to degrade REST protein." (PMID 35600406, 2022). "Previous studies have reported that REST is highly expressed in a variety of tumors, including glioma, neuroblastoma, and medulloblastoma." (PMID 33834072, 2021). "REST is not only associated with HI, but it is also associated with a predisposition to Wilm’s Tumors and has been implicated in colon cancer, small cell lung cancer, and neuroblastomas, and could suggest targeted long term follow up of the affected individuals." (PMID 34828371, 2021). "Mechanistically, NBAT-1 down-regulation enhances proliferation and invasion of neuroblastoma cells through suppression of expression of target genes as well as induction of expression of neuronal-specific transcription factor NRSF/REST." (PMID 33718173, 2021). "We found that REST is activated by inflammation in both neuroblastoma cells and primary neurons, indicating that a vast transcriptional change—common to different neural cell types—is triggered by inflammatory stimuli." (PMID 33589593, 2021). "We found that REST is activated by a variety of neuroinflammatory stimuli in both neuroblastoma cells and primary neurons, indicating that a vast transcriptional change is triggered during neuroinflammation." (PMID 33589593, 2021). "Abnormal REST activity is implicated in the genesis of many neural cancers including MB, glioblastoma, diffuse intrinsic pontine glioma (DIPG) and neuroblastoma." (PMID 33469989, 2021). "Consistent with data from other neural tumors such as medulloblastoma, neuroblastoma and glioblastoma multiforme, REST is also required for maintenance of DIPG growth in vitro and in vivo." (PMID 29435175, 2018). "Consistent with previous reports, siRNA-mediated depletion of REST resulted in the longest neurite outgrowth in Cath.a differentiated (CAD) mouse neuroblastoma cell line." (PMID 27976729, 2016). "Overexpression of REST has been found in human medulloblastomas, glioblastoma and neuroblastomas, in which REST acted as an oncogene to maintain the stem character of neural cells." (PMID 26341630, 2015).
neuroblastoma (continued). "In cancer biology, REST has been shown to play a tumor suppressor activity in epithelial cancers but an oncogenic role in brain childhood malignancies such as neuroblastoma and medulloblastoma." (PMID 22701651, 2012). "As a repressor of neuronal genes, REST promotes the proliferation of NSCs as well as neuroblastoma cell lines, whereas reduction of REST induces neuronal differentiation." (PMID 22848609, 2012). "Transcription of the first two in neuroblastoma cells is turned on by RA and inhibited by REST – a repressor of neural differentiation genes." (PMID 22848373, 2012). "The expression level of REST is found to be significantly high in neuroblastoma as well." (PMID 40006989, 2025). "A recent article found that USP3 can also regulate tumor self-renewal and proliferative capacity by interacting with the repressor element-1 (RE-1) silencing transcription factor (REST) in neuroblastoma, further demonstrating that USP3 is a potential prognostic marker for neuroblastoma." (PMID 38773075, 2024). "In neuroblastoma cells, REST was found to be reduced during differentiation." (PMID 37892159, 2023). "The frequent neuron-specific splicing of REST is involved in neuroblastoma progression, while REST activity was not affected by its mutations." (PMID 37892159, 2023). "In addition, decreased levels of REST expression were detected in several neuroblastoma cell lines, and these lines showed excessive JAK–STAT signaling pathway activation." (PMID 37373133, 2023). "REST was downregulated in mouse neuroblastoma, leading to increased neurite length." (PMID 37892159, 2023). "To investigate mechanisms of neural-specific expression of the clustered PCDH genes in the brain, we performed REST/NRSF ChIP-nexus experiments in model cells of neuroblastoma SK-N-SH and endometrial carcinoma HEC-1-B and found 5276 and 9681 REST/NRSF sites, respectively." (PMID 33849071, 2021). "REST expression is dysregulated in various tumors of neural or neural crest origin including medulloblastoma, glioblastoma, Ewings sarcoma and neuroblastoma." (PMID 29435175, 2018). "On the contrary, miR-9-2 could be inhibited by REI-silencing transcription factor (REST) in undifferentiated neuroblastoma cells, leading to a suppression of miR-9." (PMID 27563807, 2016). "REST expression may have pro-oncogenic activity in nervous tumors and is found consistently upregulated in neuroblastomas and medulloblastomas, while in small-cell lung carcinomas, loss of REST activity is observed and related to NE phenotype." (PMID 24724054, 2014). "Likewise, in neuroblastoma Neuro2a cells, it was recently demonstrated that the transcriptional activator Sp1 directly binds the synapsin I promoter, activating its transcription, and that its activity is directly modulated by the neural master regulator REST." (PMID 27223470, 2016). "However, oncogenic roles for REST have been observed in neuroblastoma and medulloblastoma." (PMID 22701651, 2012). "In studies carried out in neuroblastoma cell lines, it was observed that Sp1 increases the expression of synapsin I (SYN I), while REST prevents the binding of Sp1, decreasing SYN I." (PMID 38542313, 2024). "Suppresses neuroblastoma cell proliferation and invasion by epigenetically repressing target genes, and promotes neuronal differentiation by repressing NRSF/REST." (PMID 26087192, 2015). "In neuroblastoma, NBAT-1 affects target genes relevant to cell invasion and proliferation in epigenetics by acting as a scaffold for EZH2, and by mechanically inhibiting the NRSF/REST pathway the neural differentiation is controlled by it as well." (PMID 38243168, 2024). "While a dual activation of REST and its dominant-negative splicing isoform REST4 was observed in N2a neuroblastoma cells, primary neurons responded with a pure full-length REST upregulation in the absence of changes in REST4 expression." (PMID 33589593, 2021).
neuroblastoma (continued). "In contrast to previous reports indicating that REST is reduced in embryonic stem cells incubated with RA30, we observed that RA treatment alone was not sufficient to alter REST expression in SH-SY5Y neuroblastoma cells, but required full differentiatiation with BDNF to reduce REST mRNA levels." (PMID 27808254, 2016).
breast carcinoma (30 papers, 2010 to 2025). "Loss of function of REST was observed in 20% of breast cancer, which is associated with aggressive phenotype and poor prognosis." (PMID 40006989, 2025). "Loss of REST function is observed in approximately 20% of breast cancer cases and is associated with an aggressive phenotype and poor prognosis." (PMID 39377066, 2024). "REST target gene upregulation due to the loss of REST leads to aberrant signaling and tumor pathogenesis in NE cancers, aggressive breast cancer types, SCLC, and PCa." (PMID 39377066, 2024). "In particular, loss of REST played a role in the pathogenesis of a subset of breast cancers through the activation of the ER signaling pathway." (PMID 39273639, 2024). "In breast cancer cells, a decrease in REST expression causes an increase in LIN28A, which induces an increase in cell proliferation." (PMID 38542313, 2024). "Loss of REST function is associated with a more aggressive phenotype in breast cancer, as well as a worse prognosis in SCLC and NEPCa." (PMID 39377066, 2024). "We demonstrate a critical role for the loss of REST in aggressive breast cancer pathogenesis and provide evidence for REST as an important diagnostic marker for personalized treatment plans." (PMID 35177031, 2022). "Loss of REST function is seen in ~ 20% of breast cancers and is associated with a more aggressive phenotype and poor prognosis." (PMID 35177031, 2022). "Loss of REST function, which occurs in 20% of breast cancers (RESTless), is associated with increased relapse and disease aggression." (PMID 35177031, 2022). "In summary, we show here loss of REST plays an important role in promoting aggressive breast cancer." (PMID 35177031, 2022). "In order to further investigate loss of REST in breast cancer we analyzed REST protein levels in different breast cancer cell lines." (PMID 35177031, 2022). "Elucidation of the exact mechanism leading to loss of REST function in breast cancer requires further studies." (PMID 35177031, 2022). "Despite the frequent loss of REST, little is known about the role of REST in the molecular pathogenesis of breast cancer." (PMID 35177031, 2022). "The reason for these discrepancies is not clear at this time, but understanding the breadth and mechanism of REST loss in breast cancer is key to understanding its role in the disease, and thus should be based on robust and consistent data." (PMID 20548947, 2010). "To determine the frequency of REST protein loss in breast cancer, we developed an immunohistochemical (IHC) screen using an antibody directed to the C-terminus of REST (Atlas Antibodies, Stockholm)." (PMID 20548947, 2010). "In addition, the effect of estrogen is also amplified significantly in MCF-7 cells after REST knockdown, indicating that the loss of REST sensitizes breast cancer cells to estrogen signaling." (PMID 35177031, 2022). "Additionally, angiogenic factors including VEGFa and MMP9, REST target genes associated with migration and invasion of breast cancer cells, were upregulated in ER- or TNBC tumors." (PMID 35177031, 2022). "Our results show loss of REST may contribute to an aggressive phenotype by upregulating invasive and metastatic genes and altering steroid hormone signaling pathways in breast cancer." (PMID 35177031, 2022). "Additionally, loss of REST function (transcription factor) as a tumor suppressor was identified in colon adenocarcinoma, lung cancer, and breast cancer." (PMID 31936239, 2020). "Moreover, the loss of REST expression in breast cancer significantly correlated with recurrence and poor survival of breast cancer patients." (PMID 31936239, 2020). "To determine whether the tumor suppressor REST is lost in breast cancer, we developed a gene signature-based approach to screen for loss of REST function by measuring the expression of a cohort of REST target genes." (PMID 20548947, 2010). "We therefore asked whether aberrant REST splicing could explain the loss of REST function in breast cancer." (PMID 20548947, 2010).
breast carcinoma (continued). "Here, we test the hypothesis that loss of REST function plays a role in breast cancer." (PMID 20548947, 2010). "Given that loss of REST induces anchorage-independent growth in mammary epithelial cells, and is lost in colon and small cell lung cancers, we asked whether REST also plays a role in breast cancer." (PMID 20548947, 2010). "REST knockdown in breast cancer cells leads to the significant upregulation of KIAA1199/CEMIP (cell migration-inducing, hyaluronan-binding protein) and MMP24 (matrix metallopeptidase 24), genes which are involved in cell invasion and metastasis." (PMID 40006989, 2025). "Prior studies have shown that when REST is knocked down in breast cancer cells, MMP24 is overexpressed by RNA sequencing." (PMID 39273639, 2024). "In recent studies on breast cancer, it is found that REST directly binds to the RE1 site of CEMIP gene, inhibits CEMIP expression, and weakens the proliferative capacity of breast cancer cells." (PMID 37662915, 2023). "Our findings that REST contributes to aggressive forms of breast cancer by regulating metastatic and invasive genes provides an opportunity to further study REST as a treatment target." (PMID 35177031, 2022). "In this study, we show that REST target genes are dysregulated across different cancers and breast cancer subtypes." (PMID 35177031, 2022). "While further studies are needed to determine how REST is lost, we found aberrant expression of REST targets in breast cancer are contributing to more aggressive forms of the disease." (PMID 35177031, 2022). "We utilized gene knockdown in MCF-7 cells in the presence or absence of estrogen and progesterone followed by RNA sequencing, as well as chromatin immunoprecipitation in an attempt to understand the tumor suppressor role of REST in breast cancer." (PMID 35177031, 2022). "We next wanted to determine the role of REST target genes that were contributing to the aggressive breast cancer phenotype." (PMID 35177031, 2022). "A subset of breast cancers express normal levels of REST (repressor element 1 silencing transcription factor) mRNA but lack functional REST protein." (PMID 35177031, 2022). "Previous studies in breast cancer cell lines found that E2 was able to downregulate REST in polysomes more than total RNA." (PMID 34564315, 2021). "In breast cancer specifically, REST was identified to have significantly decreased expression in tumor compared to normal samples and REST knockdown in MCF-7 cells resulted in an increase in cell proliferation and reduced sensitivity to anticancer drugs." (PMID 33778495, 2021). "REST is a transcriptional repressor and tumor suppressor whose loss drives tumor growth of MCF7 cells in mouse xenograft model of breast cancer." (PMID 32251445, 2020). "Classification of primary breast cancer RNASeq data based on high/low CEBPB/REST/CTCF revealed that, KRT5, KRT14 and KRT17 mRNAs were significantly upregulated in CEBPBhigh and CTCFlow tumors." (PMID 30335837, 2018). "The heatmaps indicated that REST expression is inversely correlated to CEBPB expression in primary breast cancers." (PMID 30335837, 2018). "We explored the REST-dependent invasive phenotype in more detail using two breast cancer cell lines: MDA-MB-231, which is strongly invasive, and MCF-7, which is weakly invasive." (PMID 26053433, 2015). "We show that REST downregulation in weakly invasive MCF-7 breast cancer cells converts them to a more invasive phenotype, while REST overexpression in highly invasive MDA-MB-231 cells suppresses invasiveness." (PMID 26053433, 2015). "A subset of breast cancers with reduced expression of REST (i.e. REST-less tumors) display a highly aggressive phenotype that includes poor prognosis and increased likelihood of disease recurrence within the first 3 years after diagnosis." (PMID 24098490, 2013). "We show here that REST function is lost in breast cancer, at least in part via an alternative splicing mechanism." (PMID 20548947, 2010).